CRP (C-reactive protein)
Diseases named in the same sentence as CRP in open-access papers (continued):
Sharing a sentence is not in itself a finding about the gene and the disease.
Obesity (continued). "As a negative association between the circulating CRP and APOM was repeatedly reported in humans, we questioned the relationship between APOM gene expression in human subcutaneous AT and circulating hs-CRP in 300 individuals with overweight or obesity." (PMID 39303980, 2024). "However, results of previous studies are conflicting about whether obesity results in higher swollen joint count (SJC) and CRP levels, which could represent local and systemic inflammation." (PMID 38321544, 2024). "In such study, sarcopenia was associated with higher gamma-glutamyl transferase, glutamate pyruvate transaminase, high-sensitivity C-reactive protein, and diastolic blood pressure, and lower muscular and cardiorespiratory fitness compared with obesity without sarcopenia." (PMID 38443395, 2024). "Interestingly, 6 of the 8 studies included in this systematic review reporting baseline CRP values showed elevated levels (between 3 and 4.8 mg/L), reflecting that the populations evaluated, mostly patients with T2DM and obesity, possess a chronic inflammatory state." (PMID 39055657, 2024). "Our findings indicate that increased glycemia, TC, Tg, LDL-c, VLDL-c,non-HDL-c, and decreased HDL-c may be indicators of the obesity phenotype andthat increased hs-CRP, HOMA-IR, LDL-c, and non-HDL-c appear to be indicators ofthe SO phenotype." (PMID 38896593, 2024). "Women with obesity, compared to those with normal body weight, showed statistically significant differences in fasting serum levels of creatinine, uric acid, and eGFR, as well as HDL and LDL cholesterol fractions, triglycerides, ALT, GGTP, ALP, CRP, and insulin." (PMID 39769504, 2024). "Low-grade inflammation and stress oxidative condition play a role in the pathogenesis of obesity, and the serum levels of these markers, such as pro-oxidant-antioxidant balance (PAB), high-sensitivity C-reactive protein (hs-CRP), and uric acid may indicate obesity progression." (PMID 38685027, 2024). "Obesity is accompanied by chronic inflammation characterized by elevated levels of pro-inflammatory cytokines such as tumor necrosis factor-alpha (TNF-α), C-reactive protein (CRP), and interleukins (IL-1, IL-6, and IL-18), with strong correlations between these inflammatory markers and body fat." (PMID 38794702, 2024). "Nevertheless, the difference in self-assessed pain between participants with and without obesity is mild and of uncertain clinical relevance, even if significant, and does not explain the higher CRP levels seen in participants with obesity at 24-week and 48-week follow-up." (PMID 38580350, 2024). "Regarding inflammation, different kinds of cytokines, including interleukin-6 (IL-6), C-reactive protein (CRP), tumor necrosis factor α (TNF-α), as well as adipokines, may be involved in inflammatory pathways producing obesity and insulin resistance, triggering systemic stress." (PMID 38541047, 2024). "Interestingly, further MVMR analysis suggested that it was obesity, not CRP, that played a mediating role in the impact of dentures on EAA." (PMID 39003475, 2024). "Whether obesity may lend an additional dose-dependent protective effect in disease activity (independent of CRP or HAQ) or reflect social drivers of health is yet to be determined." (PMID 38337687, 2024). "One major limitation is its inability to distinguish between patients with MetS and those who are simply obese, as elevated CRP levels may be a result of obesity-related inflammation rather than the syndrome itself." (PMID 39604922, 2024). "Also, SBP (p < 0.001), HOMA-IR (p = 0.0133), CRP (p < 0.001), LDL-c (p = 0.0157), and GGT (p = 0.0277) were significantly higher in children with obesity than in children with overweight, while HDL-c (p < 0.001) concentrations were higher in children with overweight than in children with obesity." (PMID 38001309, 2024).
Obesity (continued). "Moreover, a research study on anxiety/stress disorders and CRP > 3 mg/L demonstrated that an association was observed for panic and generalized anxiety disorders with CRP, and it was attenuated regardless of obesity, multimorbidity and depression." (PMID 37873776, 2023). "However, at baseline, serum levels of CRP/hs-CRP were significantly higher in obesity patients than in those without obesity." (PMID 37798684, 2023). "The combination of obesity-related monocyte dysfunction and the suppressing effect of CRP on IL-10 secretion may explain the noted lack of association between GCF CRP and IL-10 in our results." (PMID 38138192, 2023). "Finally, the present study did not assess for potential differences in sleep and CRP outcomes between adolescents with overweight and those with obesity." (PMID 38136035, 2023). "It is well known that obesity is characterized by the elevation of proinflammatory cytokines, including tumor necrosis factor-alpha (TNF-α), interleukin-6 (IL-6), and acute-phase proteins, such as C-reactive protein (CRP), leading to chronic subclinical inflammation." (PMID 37892400, 2023). "In addition, obesity can be considered a low-grade chronic inflammatory pathology, where visceral and epicardial adipose tissue generate high plasma levels of proinflammatory cytokines such as tumor necrosis factor-alpha (TNF-α) or C-reactive protein." (PMID 35887894, 2022). "Confirming this, circulating TNF‐α and CRP were higher in individuals with than without obesity." (PMID 35293040, 2022). "Although WD-fed dams did not become obese, serum CRP and neutrophils increased, without a change in serum IL-6, indicative of mild, systemic inflammation in response to WD prior to attaining obesity." (PMID 36935840, 2022). "A comparison across the 3 groups of children with obesity, overweight and normal weight showed significant differences between these groups in the levels of lymphocytes, platelets, iron parameters, vitamin B12, uric acid, triglycerides, HDL-C, LDL-C, globulin, and CRP levels." (PMID 36498548, 2022). "However, a meta-analysis of RCTs in patients with T2DM and overweight or obesity reported that vitamin D supplementation significantly decreased circulating CRP concentrations but did not affect TNF-α or IL-6 concentrations." (PMID 35893929, 2022). "It is recognised that the severity of PCOS may be aggravated with obesity, and it has been reported that women with PCOS present higher serum concentrations of TNF and C-reactive protein (CRP) as well as monocyte and lymphocyte circulating levels, with inflammatory infiltration in ovarian tissue." (PMID 36079796, 2022). "Moreover, vitamins, like C, E, D significantly modify lipid profile, modulate oxidative stress markers (oxLDL, non-esterified fatty acids, NEFA), and inflammation (C reactive protein, CRP, adiponectin, IL-6, TNF-α), involved in obesity, hypertension, CVD and T2DM." (PMID 35214752, 2022). "Our results show, for the first time, a correlation between immunological molecules and BMI in IBS patients, suggesting that the inflammatory nature of obesity could contribute to the development of the symptoms in IBS through the stimulation and release of proteins as complement components and CRP." (PMID 36558394, 2022). "Interestingly, a recent study of 15,634 subjects in the UK Biobank showed that the effect of obesity was not mediated by blood pressure and blood biomarkers of glucose, lipids, and C-reactive protein." (PMID 35683364, 2022). "The aim of this study was to investigate differences between adolescents with and without obesity with regard to signs of vascular aging, as assessed by ultra-high-resolution ultrasound (UHRU), and to test associations with hs-CRP levels and variables reflecting adiposity and cardiovascular risk." (PMID 35846851, 2022). "However, the remaining 3 patients who were not diagnosed with MAFLD had neither T2DM, overweight/obesity, nor any other metabolic disorders than CRP." (PMID 35647047, 2022).
Obesity (continued). "CRP levels were increased in patients with obesity as compared to individuals without obesity." (PMID 35837843, 2022). "Total cholesterol, serum creatinine, and CRP levels were comparable between lean and obese participants, whereas uric acid, cystatin-c, and PRA levels were elevated in obese patients, likely reflecting obesity-induced hyperfiltration and renal damage, respectively." (PMID 34095124, 2021). "Obesity is present in almost 50% of women with SLE and adipose tissue has the capacity not only to recruit and activate mononuclear cells but also to produce key inflammatory cytokines, such as IL-6, which stimulates the production of CRP and other acute phase proteins by the liver." (PMID 34721392, 2021). "Indeed, obesity correlated with peak-CRP levels in our study while none of the other patient characteristics did." (PMID 34178545, 2021). "Moreover, the prevalence of elevated AGP (26.1% vs. 7.9%, p < 0.0001) and CRP (58.5% vs. 15.3%, p < 0.0001) was higher in obese women compared to women without obesity." (PMID 34103653, 2021). "Increased levels of C-reactive protein (CRP), a serum acute-phase reactant produced by the liver, and other proinflammatory cytokines secreted by the adipose tissue such as interleukin-6 (IL-6) and tumor necrosis factor-α (TNF-α), have been reported in patients with obesity." (PMID 33919641, 2021). "Second, some potential confounding factors of CAD like obesity, smoking, physical activity, and degree of systemic inflammation (like C-reactive protein) were not covered in this study, although COPD had been investigated in several previous studies as a proxy variable for cigarette smoking." (PMID 34295906, 2021). "In multivariate analysis, male sex (p < 0.001), constipation (p = 0.002), hemoglobin < 11.9 g/dL (p < 0.001), C reactive protein > 80 mg/L (p < 0.001), severe obesity (p = 0.049), and no proton pump inhibitor treatment (p = 0.003) were independently associated with complicated AD." (PMID 33572940, 2021). "Oral inflammation contributes differently to systemic CRP levels between different states of adiposity depending on whether obesity is present or not." (PMID 32827080, 2021). "Obesity and T2DM are characterised by chronic low-grade inflammation with abnormal expression and production of multiple inflammatory mediators such as increased levels of TNF, C-reactive protein (CRP), plasminogen activator inhibitor-1 and interleukins (IL-1, IL-6)." (PMID 34900829, 2021). "In addition, a meta-analysis confirms observations that IL-6 and TNF-α levels are related to obesity but not PCOS occurrence, whereas CRP levels are elevated in PCOS independent of obesity." (PMID 32934654, 2020). "Compared to those with BMI<30, patients with obesity had lower ferritin (444 vs 637 ng/mL; p<0.001) and lower D-dimer (293 vs 350 mcg/mL; p = 0.009), non-significant differences in CRP (72.8 vs 84.1 mg/L, p = 0.099), and higher LDH (375 vs 340, p = 0.009) on the first hospital day." (PMID 33326480, 2020). "As such, it might be argued whether obesity could have a major impact on CRP values, as those with NAFLD were heavier than those without NAFLD (BMI 30.6 vs 27.1, p = 0.003)." (PMID 33031439, 2020). "It has also been shown that calprotectin may be more useful for both detecting and monitoring inflammation in adults, related to metabolic complications of obesity, as compared with conventional inflammatory markers, such as white blood cell (WBC) count or C-reactive protein (CRP)." (PMID 33081030, 2020). "Our results indicates that in non-obese, apparently healthy women GG homozygosity of the G-308A TNF-α polymorphism is associated with enhanced low grade inflammation assessed by serum CRP-hs concentrations, and occurrence of obesity does not affect significantly CRP-hs levels in GG homozygotes." (PMID 30900134, 2020).
Obesity (continued). "Obesity alone, in the absence of overt disease, is frequently accompanied by subclinical systemic inflammation marked by increased circulating levels of proinflammatory indicators such as CRP and leptin." (PMID 32326613, 2020). "Moreover, correlation analysis demonstrated that lncRNA RP11-20G13.3 in adipose tissue from obese and non-obese children was positively associated with obesity indices, circulating levels of insulin, LDL-C,and hs-CRP." (PMID 32368256, 2020). "There was a trend for high-sensitive CRP Z-score through each metabolic health phenotypes, with the CRF attenuating the association of high-sensitive CRP Z-score levels, particularly in the MHNO and in adolescents with obesity, regardless of their metabolic profile (F = 4.423, p = 0.03)." (PMID 32443557, 2020). "Metabolic NAFLD complications, obesity, insulin resistance and type 2 diabetes involve a chronic “low-grade inflammation”, resulting in the increase in obesity-related inflammatory molecules, such as: TNF-alpha, IL-1beta, IL-6, IL-1Ra, and C-reactive protein (CRP)." (PMID 33306695, 2020). "The reaction to obesity-related inflammation is the activation of the NF-ĸB transcription factor, which enhances, among others, the production of pro-inflammatory interleukins such as IL-1, IL-6 and TNF-α, and the concentration of C-reactive protein also increases." (PMID 32872598, 2020). "This reduction of acute CRP, even though not significant, might demonstrate some effect of nonanimal CS in counterbalancing the low-grade inflammation usually seen with obesity." (PMID 33297347, 2020). "Thus, future clinical studies should focus on the feasibility of using anti-inflammatory strategies for patients with obesity and MDD, who might possibly benefit from reducing systemic inflammatory biomarkers such as CRP." (PMID 33488420, 2020). "It is possible that chronic low-grade elevation of CRP may pass on a “cheating” message of non-communicable inflammation to the body, which then over-reacts to this cheating message and develops obesity." (PMID 32154244, 2020). "It is also well accepted that obesity promotes chronic low-grade inflammation, a systemic condition characterized by increased systemic levels of some inflammatory cytokines (TNF-α, IL-1β, IL-6) among other inflammatory mediators such as C reactive protein (CRP)." (PMID 31684076, 2019). "The aim of this study was to determine if CK was related to obesity and metabolic syndrome in this Middle Eastern population and whether CK was higher in those women with PCOS, perhaps due to elevated inflammatory markers, including C-reactive protein (CRP)." (PMID 31608014, 2019). "Moreover, CpGs in the VMP1/MIR21 locus are also among the top hits in several previous EWAS, including chronic inflammation marker C-reactive protein (CRP), cardiovascular biomarker GDF-15, obesity, childhood-onset Crohn’s disease, and inflammatory bowel disease." (PMID 30867049, 2019). "However, another study conducted in older adults showed that the interactions of CRP with obesity were not significant." (PMID 30728031, 2019). "However, published data reported a negative correlation between vaspin and CRP, demonstrating that vaspin has anti-inflammatory and anti-atherosclerotic effects in the contexts of obesity-related inflammation and CVD." (PMID 31771561, 2019). "Both obesity and O3I were significant predictors of CRP, but not for TNF-α or Il-6." (PMID 31892115, 2019). "As the role of CRP level on MDD and obesity association was no consistent across all adiposity measures in our study, it is important that this hypothesis would be confirmed in others longitudinal studies to rule out that this result was observed by chance." (PMID 31800914, 2019). "Evidence shows that obesity results in chronic low-grade inflammation, which may elevate CRP levels due to the adipose tissues releasing IL-6 and TNF-α and inducing the synthesis of CRP by the liver." (PMID 30065944, 2018).
Obesity (continued). "Although a concomitant increase in CRP and plasma leptin has been observed in obesity, it is not clear whether elevation in CRP is due to acute inflammation or due to adipose tissue expansion or both." (PMID 29910808, 2018). "In obesity, TNF-α, Il-1β, and IL-6 may induce the hepatic release of C-reactive protein (CRP)." (PMID 29189992, 2018). "At the baseline, the subjects with obesity had significantly higher body weight, BMI, WC, soft lean mass, visceral fat mass, waist to hip ratio, fasting glucose, insulin, HOMA-IR, triglycerides, uric acid, WBC, hs-CRP, ALT, γ-GT, C-peptide, and NFS than those in the normal BMI group." (PMID 30458048, 2018). "Indeed one of our previous studies found that higher levels of circulating IL-6 and CRP in MDD patients may be explained, at least in part, by obesity." (PMID 28670290, 2017). "A further evidence of the link between, obesity, inflammation and cardiovascular diseases in patients with psoriasis is provided by several studies reporting a correlation between PASI score and increased of CRP levels and between psoriasis and waist circumference." (PMID 28176237, 2017). "The significant relationship between CRP and depression in the underweight group suggested that not only obesity but also a low BMI could explain a substantial portion of the inflammation-depression link." (PMID 28128231, 2017). "However, in the other BMI groups (from normal weight to obesity), the CRP-depression relationship was no longer significant (p > 0.05)." (PMID 28128231, 2017). "Some studies reported increased CRP serum levels in OSAS patients, but other studies failed to verify this association and suggested that external factors, such as obesity, may influence the results." (PMID 27843647, 2016). "Two studies reported similar levels of CRP in periodontitis patients with and without obesity." (PMID 27795608, 2016). "Two studies reported similar levels of CRP in patients with periodontitis with and without obesity." (PMID 27795608, 2016). "Since BMI, T2D and MetS are not completely independent of inflammation level, we also performed an analysis where in the multivariable logistic regression model hs-CRP was modelled together with obesity grade with and without T2D, and also modelled together with MetS." (PMID 26474291, 2015). "Similarly, there was no multiplicative interaction of obesity with the summed health behavior variable on CRP (β = 0.05, p = 0.58)." (PMID 26106588, 2015). "Although CRP is not a cytokine, it is a useful inflammatory marker for obesity." (PMID 26380303, 2015). "Furthermore obesity as well as STEMI is considered a low-grade inflammatory state, as demonstrated by increased levels of the pro-inflammatory cytokines interleukin-6 and tumor necrosis factor-alpha, and acute phase proteins such as C-reactive protein." (PMID 26162888, 2015). "Moreover, systemic inflammatory markers SAA and CRP were not positively associated with increased MAP3K8 adipose tissue levels, suggestive of a redundant role of MAP3K8 in obesity-induced low-grade systemic inflammation." (PMID 24586913, 2014). "The greater mortality associated with sarcopenia and sarcopenic obesity (but not obesity) remained after adjustment for prevalent MI, prevalent stroke, HDL-C, SBP, FEV1, CRP, D-dimer, vWF, and weight loss (sarcopenic, HR = 1.34, 95% CI = 1.15–1.57; sarcopenic obese, HR = 1.44, 95% CI = 1.10–1.90)." (PMID 24428349, 2014). "Obesity is characterized by a condition of low-grade chronic inflammation, and it is well known that adipocytes express TNF-α and may produce 30%–40% of circulating levels of IL-6, the main regulator of CRP production in the liver." (PMID 23509804, 2013). "Obesity is considered as an inflammatory status, because proinflammatory molecules, expressed by adipose tissue such as leptin, TNF-α, IL-6, TGF- β1, adiponectin and C-reactive protein, are increased in obese subjects, especially in females (mainly C-reactive protein and leptin)." (PMID 24028436, 2013).